TRPV4 (transient receptor potential cation channel subfamily V member 4)
Diseases named in the same sentence as TRPV4 in open-access papers (continued):
Sharing a sentence is not in itself a finding about the gene and the disease.
myocardial infarction (10 papers, 2017 to 2025). Gross necrosis of the myocardium, as a result of interruption of the blood supply to the area, as in coronary thrombosis. "TRPV4 in mouse heart was shown to promote post myocardial infarction-induced ventricular fibrosis that was associated with cardiac dysfunction and poor survival, and those effects were absent in TRPV4 knock-out mice." (PMID 36277180, 2022). "Moreover, TRPV4 loss exhibits a substantial protective effect post-myocardial infarction, reducing cardiac fibrosis and preserving cardiomyocyte integrity in the infarct-surrounding area." (PMID 40863131, 2025). "More recently, TRPV4 channels have been involved in fibrosis formation following myocardial infarction by modulating the Rho/MRTF-A pathway in cardiac fibroblasts (FB)." (PMID 38338818, 2024). "The role of TRPV4 in cardiac remodeling has been investigated in the context of myocardial infarction and subsequent fibrosis, with a focus on TRPV4 channels expressed in non-excitable cardiac fibroblasts." (PMID 38256251, 2024). "The same group recently found that inhibition of TRPV4 protects against fibrosis formation following myocardial infarction by reducing FB’s differentiation through the mechanosensitive transcriptional Rho/Rho kinase/MRTF-A pathway." (PMID 38338818, 2024). "Activation of TRPV4 is involved in hypoxia/reoxygenation injury and congestive cardiac failure, and the TRPV4 antagonist HC-067047 significantly reduced the myocardial infarction area and improved cardiac function in an ischemia–reperfusion (I/R) model." (PMID 38279064, 2024). "A similar effect was observed after the administration of 0.8 μM GSK101, a potent agonist of the mechanosensory channel Trpv4 with a demonstrated cardioprotective effect when administered after acute myocardial infarction in rats." (PMID 38799508, 2024). "This study showed the role of TRPV4 in age-dependent arrhythmia following I/R, suggesting a possible therapeutic target for TRPV4 following myocardial infarction in aging." (PMID 34867442, 2021). "In WT and TRPV4KO mice subjected to myocardial infarction (MI) by permanently ligating LAD, 2D echocardiography showed that the absence of TRPV4 preserved cardiac function in TRPV4KO mice compared to WT mice in the following 8 weeks after MI." (PMID 34831281, 2021).
congestive heart failure (9 papers, 2017 to 2024). Failure of the heart to pump a sufficient amount of blood to meet the needs of the body tissues, resulting in tissue congestion and edema. "Conversely, the WT mice subjected to MI or congestive heart failure showed an upregulation of TRPV4 channels and profibrotic genes compared to the untreated WT mice, which led to increased intracellular Ca2+ levels and amplified the pathological fibrosis process." (PMID 37371124, 2023). "TRPV4 inhibitors further have the potential to treat certain cancers with high safety, as demonstrated by the success of a Phase II clinical study involving the TRPV4 inhibitor GSK2798745 in patients with congestive heart failure." (PMID 37369706, 2023).
fibrosis (9 papers, 2016 to 2025). the formation of excess fibrous connective tissue in an organ or tissue in a reparative or reactive process. "Additionally, increased TRPV4 expression in the myocardium of diabetic mice is linked to cardiac fibrosis, indicating a broader role for TRPV4 in CVDs that may be mediated through ECM regulation in aECs." (PMID 41388869, 2025). "Since Ca2+ signaling involves multiple pathways, we will provide detailed information on TRPV4 and focus on Ca2+ flux through TRPV4 channels because of its implications in fibrosis below." (PMID 41511340, 2025). "Additional evidence for TRPV4 involvement was obtained by showing that the severity of the inflammatory fibrosis was attenuated to a similar extent following systemic daily administration of a TRPV4 antagonist, HC-067047, for 20 days." (PMID 28030558, 2016). "Taken together, TRPV4 gene ablation reduces both alkali-burn -induced inflammatory reaction and subsequent fibrosis in mouse corneas." (PMID 28030558, 2016). "Our results reveal that TRPV4 blockade prevented abnormal changes in atrial myocyte electrophysiology and ameliorated atrial fibrosis and inflammation in SP rats; therefore, it might be a promising strategy to treat AF, particularly postoperative AF." (PMID 33119551, 2020). "Therefore, in the skin fibrosis model, TRPV4′s effect on fibrosis development could also be attributed to its induction of fibroblasts’ collective migration and cell state transition toward myofibroblasts." (PMID 38256251, 2024).
migraine (9 papers, 2019 to 2025). "A TRPV4 antagonist inhibited these behavioral responses, suggesting that this channel can be a potential therapeutic target for anti-migraine drugs." (PMID 37175602, 2023). "Although little is known about the relationship between TRPV4 and migraine, its function is particularly intriguing as changes in intracranial pressure are known to affect headaches." (PMID 37175602, 2023). "TRPV1 and TRPV4 are abundantly expressed in primary sensory neurons and play a primary role in migraine pain." (PMID 37303955, 2023). "Another finding supporting the role of TRPV4 in migraine is that solutions applied to the surface of the dura mater that increase or decrease osmolarity can sensitize trigeminal afferents." (PMID 36614146, 2022). "Unfortunately, most of the results obtained from preclinical studies provide only indirect evidence for a link between TRPV4 and migraine." (PMID 36614146, 2022). "Little work currently exists surrounding TRPV4 and migraine and this is the area that needs to most future exploration to evaluate this channel as a potential anti-migraine drug target." (PMID 30970581, 2019). "The transient receptor potential (TRP) channels, particularly TRPV1 (activated above 43 °C) and TRPV4 (responding to 24–35 °C), play a key role in migraine development by triggering inflammation and releasing pro-inflammatory agents like calcitonin gene-related peptide (CGRP) and substance p." (PMID 41302667, 2025). "As the main members of the TRP family, the polymorphisms of TRPV1, TRPV4 and TRPM8 genes may play an important role in the occurrence and development of migraine." (PMID 37303955, 2023). "Based on these, the functions and trigeminal localization of TRPV4 may fit some aspects of migraine, such as the characteristic throbbing pain that is aggravated by routine movements, coughing, or sneezing." (PMID 36614146, 2022). "Recently, TRPV4 was shown to be expressed in dural afferents, and its activation in the dura of freely-moving rats could produce migraine-like behavior such as cutaneous allodynia." (PMID 31336748, 2019). "Although dural afferents are known to be mechanically sensitive, whether TRPV4 activation that contributes to migraine is due to mechanical stimulation or another endogenous mechanism remains to be elucidated." (PMID 31336748, 2019). "As a mechanosensitive channel, TRPV4 has attracted increasing interest in the context of migraine." (PMID 31336748, 2019). "Other TRP channels, such as TRPV4, TRPM3, TRPC4 and TRPM8, remain reliable candidates to be involved in migraine pain signaling with potential to be drug targets." (PMID 38221631, 2024). "However, transient receptor potential (TRP) channels have been repeatedly linked to the disorder, including TRPV1, TRPV4, TRPM8, and TRPA1, based on their activation by pathological stimuli related to attacks, or their modulation by drugs/natural products known to be efficacious for migraine." (PMID 30970581, 2019). "This may be due to limited research concerning TRPV4, and the fact that dual inhibition strategies have not yet been considered for the treatment of migraine." (PMID 31336748, 2019).
pulmonary hypertension (9 papers, 2017 to 2024). Increased pressure within the pulmonary circulation due to lung or heart disorder. "TRPV4, a Ca2+-permeable cation channel, plays an important role in the vasculature and is implicated in the regulation of cardiovascular homeostasis processes such as blood pressure, vascular remodeling, and pulmonary hypertension and edema." (PMID 33981725, 2021). "Transient receptor potential 4 (TRPV4) channels expressed on arterial adventitia fibroblasts play important roles in the development of adventitia remodeling induced by pulmonary hypertension." (PMID 39425532, 2024). "It is known that TRPV4 protein is upregulated in the artery adventitia of rats subjected to chronic hypoxia and monocrotaline-induced pulmonary hypertension." (PMID 39425532, 2024). "4α-PDD induces extracellular Ca2+ entry and TRPV4 overexpression increases basal [Ca2+]i in hypoxic PASMCs, resulting in myogenic tone enhancement and the development of hypoxia-induced pulmonary hypertension." (PMID 33981725, 2021). "Our results further support the notion that manipulation of TRPV4 function may offer a novel therapeutic strategy for the treatment of hypoxia-related pulmonary hypertension." (PMID 32399392, 2020). "Therefore, TRPV4 activators may serve as new therapeutic option in the fight against pulmonary arterial hypertension (PAH)." (PMID 33917551, 2021). "Hence, we hypothesize that CYP-EET regulates the agonist-induced vasoconstriction through TRPV4 activation in pulmonary hypertension." (PMID 32399392, 2020). "Furthermore, TRPV1 and TRPV4 channels may control vascular remodeling by promoting VSMC proliferation and migration under pathological conditions, such as pulmonary hypertension." (PMID 32038296, 2019).
Sepsis (9 papers, 2015 to 2024). Sepsis is defined as life-threatening organ dysfunction caused by a dysregulated host response to infection. "The current study suggests that pharmacologic inhibitors of TRPV4 can reduce the production of proinflammatory cytokines, restore vascular endothelial cell function, and decrease sepsis-associated hyperinflammatory response and mortality in the septic rat." (PMID 39355841, 2024). "TRPV4 has been reported to be involved in the hyperinflammatory response and mortality associated with sepsis." (PMID 38731999, 2024). "Here, we show that TRPV4 channels are involved in the hyper-inflammatory response and mortality associated with sepsis." (PMID 27653046, 2016). "The cation channel transient receptor potential vanilloid 4 (TRPV4) is expressed in vascular endothelium and causes vasodilatation, but excessive TRPV4 activation leads to profound hypotension and circulatory collapse - key features of sepsis pathogenesis." (PMID 26064477, 2015). "It is conceivable therefore, that inflammation-induced upregulation of endogenous factors could contribute to sepsis-associated circulatory failure via excessive TRPV4 activation." (PMID 26064477, 2015). "By extension, blockade of TRPV4 activity may be expected to attenuate the circulatory dysfunction that underlies sepsis pathogenesis." (PMID 26064477, 2015). "We hypothesised that loss of TRPV4 signaling would protect against cardiovascular dysfunction in a mouse model of sepsis (endotoxaemia)." (PMID 26064477, 2015). "Recent reports have linked excessive TRPV4 activation to lethal endothelial failure, oedema formation, hypotension and circulatory collapse (Sonkusareet al., 2012;Willetteet al., 2008), suggesting it may play a key role in sepsis pathogenesis." (PMID 26064477, 2015). "In models of sepsis, inhibition of TRPV4 through genetic deletion or pharmacological block has been shown to be protective." (PMID 33193423, 2020). "That is, excessively low or excessively high doses of TRPV4 agonists cannot effectively treat sepsis." (PMID 33193423, 2020). "In both LPS and CLP models of sepsis inhibition of TRPV4 significantly decreased systemic cytokines, maintained endothelial cell function, and reduced mortality in mice." (PMID 33193423, 2020). "Supporting an essential role for TRPV4 channels in the development of sepsis, TRPV4−/− mice treated with LPS had higher survival rates (median survival = 2.2 days; 7-day survival = 40%) compared to normal mice (median survival = 1.6 days; 7-day survival = 0%)." (PMID 27653046, 2016). "To determine if post-LPS inhibition of TRPV4 channels afforded protection against sepsis, we examined survival rates in the LPS model in mice administered a TRPV4 antagonist 2 or 4 hours after LPS." (PMID 27653046, 2016). "We conclude that the TRPV4 channel is a potential new therapeutic target in the critical, early hyper-inflammatory phase of sepsis that precedes pro-inflammatory cytokine production." (PMID 27653046, 2016). "Further supporting the essential role for TRPV4 channels in sepsis, TRPV4−/− mice treated with LPS also had increased survival rates compared to normal mice." (PMID 27653046, 2016). "Taken together, these results indicate that the TRPV4 channels participate in the early events of sepsis development and that TRPV4 channel antagonists confer protection against sepsis-induced mortality when administered early in disease progression." (PMID 27653046, 2016). "Although these findings point to a crucial role for TRPV4 channel activity in the development of sepsis, the specific site at which TRPV4 antagonists act to suppress cytokine release in vivo remains unidentified." (PMID 27653046, 2016). "In this study, we provide the first evidence that inhibition of TRPV4 channels reduces the hyper-inflammatory response in sepsis and increases survival." (PMID 27653046, 2016).
Sepsis (continued). "We therefore tested the effects of the TRPV4 antagonist GSK219 on the levels of sepsis-induced circulating cytokines, measuring serum concentrations 3 and 18 hours after LPS injection in control (LPS alone) and GSK219-pretreated (LPS + GSK219) mice." (PMID 27653046, 2016). "Our data suggest that treatment with TRPV4 antagonists would potentially be more beneficial in a hyper-inflammatory phase of sepsis compared to a phase of a compensatory anti-inflammatory response or a mixed anti-inflammatory response." (PMID 27653046, 2016). "Survival was increased dramatically (60–70%) in both models when mice were treated with the TRPV4 antagonist prior to the induction of sepsis." (PMID 27653046, 2016). "For instance, interfering with the endogenous function of TRPV4 in the early stages of sepsis could be dangerous, as TRPV4 is necessary for host responses to mycobacteria in the early phases of infection." (PMID 38730655, 2024). "Emerging data indicate that TRPV4, particularly the alveolar macrophage TRPV4, plays a beneficial role in the initiation and development of nonsterile or infectious-associated (e.g., sepsis, LPS) ALI/ARDS." (PMID 36539808, 2022). "It is hypothesized that a balance in TRPV4 activation is necessary for optimal improvement in sepsis severity." (PMID 33193423, 2020). "We found that LPS-induced sepsis caused an increase in proMMP-9 and P-selectin, regardless of TRPV4 antagonist treatment." (PMID 27653046, 2016). "Local targeting of TRPV4 signalling may be more beneficial than global inhibition in sepsis treatment." (PMID 26064477, 2015). "Supplementation of drinking water with orally available TRPV4 antagonists (Thorneloeet al., 2012) would be required to further elucidate the effects of TRPV4 blockade on cardiovascular function in endotoxaemia or sepsis." (PMID 26064477, 2015). "Overall, our data do not support a major role for TRPV4 in sepsis-associated cardiovascular dysfunction." (PMID 26064477, 2015). "Regardless of underlying mechanisms, based on data obtained in this study, TRPV4 does not appear to be a viable target in the treatment of sepsis-associated cardiovascular dysfunction." (PMID 26064477, 2015). "Because the broad range of cytokines suppressed by TRPV4 channel blockade resembles the repertoire of cytokines produced by macrophages, we speculate that TRPV4 channel antagonists decreased hyper-inflammatory cytokine levels during sepsis development by blocking macrophage TRPV4 channels." (PMID 27653046, 2016). "Here, using three different mouse models, we investigated the contribution of TRPV4 channels to the development of sepsis, and sought to determine whether pharmacological blockade of these channels with potent, selective TRPV4 antagonists exerts a protective effect." (PMID 27653046, 2016). "Numerous endogenous agonists and regulators of TRPV4, including anandamide (Vargaet al., 1998), arachidonic acid and its metabolites (Bruegelet al., 2012), protein kinase A (Yanget al., 1997), shear stress and temperature have been shown to be upregulated or altered in sepsis." (PMID 26064477, 2015). "However, further studies in which research conditions are optimised may yet uncover evidence of a vasoregulatory role for TRPV4 in sepsis." (PMID 26064477, 2015). "Contrary to the initial hypothesis, loss of TRPV4 signaling (either through gene deletion or pharmacological antagonism) did not attenuate sepsis-induced cardiovascular dysfunction: in fact, pathology appeared to be modestly exaggerated in mice lacking TRPV4." (PMID 26064477, 2015). "Based on observations that excessive TRPV4 activation can cause profound hypotension, endothelial failure and circulatory collapse (Willetteet al., 2008), we hypothesised that enhanced TRPV4 activity may contribute to haemodynamic and vascular dysfunction during sepsis." (PMID 26064477, 2015).
Sepsis (continued). "Pharmacological inhibition of TRPV4 channels in mice reduced mortality in lipopolysaccharide and cecal-ligation-and-puncture models of sepsis, but not in a tumor necrosis factor-α (TNFα)-induced sepsis model." (PMID 27653046, 2016). "In the LPS-induced sepsis model, the median survival of mice that were not treated with a TRPV4 antagonist was 1.6 days, and no mice survived more than 3 days after LPS injection." (PMID 27653046, 2016). "TRPV4 KO mice also exhibited the lowest blood pH of all groups during sepsis, but this was not significantly different from the mildly acidotic basal pH in these animals." (PMID 26064477, 2015). "Additionally, it has been suggested that TRPV4 and TRPM2 antagonists may have therapeutic potential in treating sepsis." (PMID 38731999, 2024). "In line with our data, TRPV4 inhibition showed no protective effect in TNF-α induced sepsis, whereas it does in LPS induced sepsis." (PMID 32974355, 2020).
axonal neuropathies (8 papers, 2013 to 2023). "Transient receptor potential vanilloid 4 (TRPV4) mutations are known to cause inherited axonal neuropathies and skeletal dysplasia." (PMID 37706131, 2023). "Some mutations in TRPV4 that augment Ca2+ influx have been shown to underlie the pathogenesis of TRPV4-linked axonal neuropathies." (PMID 28663724, 2017). "A gain-of-function of TRPV4 mutation increased its Ca2+ channel activity, which underlies the pathogenesis of TRPV4-linked axonal neuropathies." (PMID 28663724, 2017). "Our finding expands further the clinical variability among TRPV4 mutations and highlight that the presence of skeletal abnormalities in a patient with an axonal neuropathy or neuronopathy should raise the possibility of TRPV4 gene mutations." (PMID 25900305, 2015). "The presence of intra-cytoplasmic basophilic inclusions in muscle biopsies of patients with axonal neuropathies should raise the possibility of mutations either in TRPV4 or in heat shock protein genes." (PMID 25900305, 2015). "Supporting this possibility, a mis-sense mutation that increases calcium flux through TRPV4 channels is associated with several axonal neuropathies." (PMID 23386813, 2013). "Therefore, TRPV4 increased function mutations lead to a more intracellular influx of Ca2+ and emerge to trigger the etiology of TRPV4-associated axonal neuropathies." (PMID 37332910, 2023). "Studies have implicated that TRPV4 gene mutation has been connected to three apparent axonal neuropathies, including Scapuloperoneal spinal muscle atrophy (SPS MA), Congenital distal spinal muscle atrophy (CDSMA), and Charcot Marie Tooth disease type 2C (CMT2C)." (PMID 37332910, 2023).